ABCC3 (ATP binding cassette subfamily C member 3)
Diseases named in the same sentence as ABCC3 in open-access papers (continued):
Sharing a sentence is not in itself a finding about the gene and the disease.
epilepsy (3 papers, 2021 to 2025). A brain disorder characterized by episodes of abnormally increased neuronal discharge resulting in transient episodes of sensory or motor neurological dysfunction, or psychic dysfunction. "The hypomethylation of ABCC3 has been observed in LGG patients with epilepsy, which is associated with unfavorable prognoses." (PMID 37662954, 2023). "This indicates that PDPN and ABCC3 are risk genes, and INA is a protective gene for LGG patients with epilepsy." (PMID 34336837, 2021). "In this study, the high expression of ABCC3 and PDPN genes was found in the high immune score group and was related to the poor prognosis of LGG patients with epilepsy." (PMID 34336837, 2021). "An immune-related gene signature was established based on ABCC3, PDPN, and INA, which can be used to predict the prognosis, immune infiltration status, immunotherapy and chemotherapy response of LGG patients with epilepsy." (PMID 34336837, 2021). "This suggests that the hypomethylation of ABCC3 and PDPN is present in LGG patients with epilepsy who have high immune score and poor prognosis." (PMID 34336837, 2021). "Further, three prognostic DEGs (ABCC3, INA, and PDPN) were identified between high and low immune score groups in LGG patients with epilepsy." (PMID 34336837, 2021).
malignant glioma (3 papers, 2010 to 2022). A grade III or grade IV glioma arising from the central nervous system. "Of the 12 overexpressed genes, ABCC3, COL8A1, IBSP and PDPN are reportedly associated with GBM, while CTHRC1, PDLIM4 and MYL9 are associated with high-grade and malignant gliomas, respectively." (PMID 35456975, 2022).
melanoma (3 papers, 2005 to 2021). A malignant, usually aggressive tumor composed of atypical, neoplastic melanocytes. "Similarly, ATP Binding Cassette Subfamily C Member 3 (ABCC3) was shown to be significantly upregulated in our resistant melanoma cell lines compared to our sensitive melanoma cell lines." (PMID 34885166, 2021).
non-small cell lung carcinoma (3 papers, 1995 to 2016). A group of at least three distinct histological types of lung cancer, including non-small cell squamous cell carcinoma, adenocarcinoma, and large cell carcinoma. "In non-small cell lung cancer ABCC3 was shown to be highly expressed and it served as a drug resistance marker." (PMID 27171227, 2016).
Obesity (3 papers, 2022 to 2024). Accumulation of substantial excess body fat. "HFD-fed mice treated with probiotics had significantly lower DEGs of Abcc3 and Aldh3a2 in the liver, suggesting that the probiotic shows protective effects against diet-induced obesity and its related metabolic liver diseases/disorders." (PMID 35743193, 2022). "Additionally, this risk of nephrotoxicity is supported by our finding of a 2.2-fold down-regulation of ABCC3 mRNA in the kidneys of obese/overweight subjects, which is also in support of findings from a murine model of obesity." (PMID 39412582, 2024).
asthma (2 papers, 2019 to 2024). "In a previous study that analyzed the expression of 48 known ABC transporters in smokers with and without COPD as well as asthma diagnosis, three of them, ABCB6, ABCC1, and ABCC3, were shown to be upregulated by exposure to cigarette smoke." (PMID 38442133, 2024).
chronic myelogenous leukemia (2 papers, 2020 to 2024). "An overexpression of ABCC3 was found in patients in blast crisis of chronic myeloid leukemia with disease recurrence, and ABCC3 can promote imatinib efflux being responsible for the failure in imatinib-target treatments." (PMID 38731966, 2024).
hepatotoxicity (2 papers, 2020 to 2024). Toxicity that causes injury to the liver or impairs the liver function. "For ABCC3 rs4793665, 90.5% of patients with the TT genotype developed grade 3–4 hepatotoxicity, compared to 43.2% of patients with TC or CC genotypes (p < 0.001 in a dominant model)." (PMID 39771563, 2024). "The occurrence of ABCC3‐1767GA was almost similar in tobacco using HIV patients without hepatotoxicity compared with nonusers (27.9% vs. 28.4%, OR = 1.03, 95% CI: 0.42–2.50, p = .88)." (PMID 32212330, 2020). "The occurrence of ABCC3‐1767GG, 1767GA, 1767GA+AA genotypes and ABCC3‐1767A allele found almost similar among HIV patients without hepatotoxicity and healthy controls (69.5% vs. 67.7%; 28.2% vs. 32.1%; 30.53% vs. 33.33%; 16.41% vs. 17.30%, respectively)." (PMID 32212330, 2020).
hyperbilirubinaemia (2 papers, 2017 to 2025). "The sister protein MRP3, encoded by ABCC3, is expressed at the sinusoidal membrane and pumps bilirubin diglucuronide (BDG) back into the blood, which leads to conjugated hyperbilirubinaemia." (PMID 29259555, 2017).
juvenile idiopathic arthritis (2 papers, 2017 to 2022). Juvenile idiopathic arthritis (JIA) is the term used to describe a group of inflammatory articular disorders of unknown cause that begin before the age of 16 and last over 6 weeks. "In patients with juvenile idiopathic arthritis treated with MTX, ABCC3 rs4793665 had significant effects on the therapeutic response." (PMID 27566582, 2017).
lung adenocarcinoma (2 papers, 2022). A carcinoma that arises from the lung and is characterized by the presence of malignant glandular epithelial cells. "Among them, CRABP2, KAT2A, BIRC5, ABCC3, PLK1, IGHG1, and EPCAM were upregulated in lung adenocarcinoma samples, while FABP4 was downregulated in lung adenocarcinoma samples." (PMID 35909589, 2022).
ovarian tumor (2 papers, 2019 to 2023). "Increased levels of various transporters, such as ABCA1, ABCB5, and ABCC3/MRP3, have been demonstrated in ovarian tumour tissues, and an increased expression of ABCA1, ABCB1/MDR1/P-GP, and ABCG2/BCRP has been demonstrated in ovarian CSCs." (PMID 38201468, 2023). "Moreover, it has been reported that there were high levels of ABCA1, ABCB5, and ABCC3/MRP3 expressions in ovarian tumor tissues and high levels of ABCA1, ABCB1/MDR1/P-GP, and ABCG2/BCRP expression in ovarian CSCs." (PMID 31810474, 2019).
renal cell carcinoma (2 papers, 2016 to 2025). "In addition, upregulation of other members of the efflux transporter family—specifically ABCC3–6, ABCC2–6, and ABCC3/ABCC5—has been identified as a hallmark of miR-21-mediated MDR in renal cell carcinoma cells." (PMID 41463125, 2025).
adenomyosis (1 paper, 2020). The growth of endometrial tissue inside the muscular wall of the uterine corpus. "SPP1, LIF, TCN1 and CLDN4 were common to adenomyosis and healthy groups of genes, while ANXA2, EDNR8, MMP26, DEPP1, ABCC3, CDA and SLC1A1 were common to endometriosis and healthy groups." (PMID 32933042, 2020).
Anxiety (1 paper, 2019). Intense feelings of nervousness, tension, or panic often arise in response to interpersonal stresses. "Common variants in MTR, PPARA, ABCC3, CALML5, CACNB2 and PCDHB10 genes were associated with deficits in neurocognitive tests performance, whereas a variant in SLCO1B1 and EPHA5 genes was associated with anxiety and depression." (PMID 31181069, 2019). "Functionally predicted germline common variants in MTR, PPARA, SLCO1B1, ABCC3, CALML5, CACNB2 and PCDHB10 genes were found to be significantly associated with deficits in neurocognitive tests performance, whereas a variant in EPHA5 gene was significantly associated with both anxiety and depression." (PMID 31181069, 2019).
atherosclerosis (1 paper, 2009). A disease characterized by the build-up of fatty material and calcium deposition in the arterial wall resulting in partial or complete occlusion of the arterial lumen. "Coronary and carotid gene expression profiles evidenced the up-regulation of the ABCC3 gene, a new member of the ATP-binding-cassette family associated with atherosclerosis in mouse." (PMID 19134193, 2009).
breast tumors (1 paper, 2016). "Additionally, high levels of expression of Nrf2, ABCC1, ABCC3 plus NAD(P)H dehydrogenase quinone-1 in breast tumors of patients at the time of diagnosis were prognostic of poor survival after tamoxifen therapy." (PMID 26883574, 2016). "Those patients, who had ERα-positive breast tumors with low expression of Nrf2, ABCC1, ABCC3 and NQO1 at the time diagnosis, had a better prognosis after tamoxifen treatment than those patients that were high expressers, with an HR value as high as 4.2." (PMID 26883574, 2016). "Thus, evaluating breast tumors of patients for the expression of Nrf2, ABCC1, ABCC3 and NQO1 warrants formal assessment as predictive markers for tamoxifen response." (PMID 26883574, 2016).
cutaneous leishmaniasis (1 paper, 2022). Leishmaniasis affecting the skin. "In this study, we evaluated ABCI4, ABCG2, ABCC7, ABCB4, and ABCC3 genes expression in Leishmania isolated from patients with non-healing cutaneous leishmaniasis and treatment response isolates." (PMID 35710996, 2022).
esophageal cancer (1 paper, 2023). A primary or metastatic malignant neoplasm involving the esophagus. "FAT1 knockdown may enhance stemness and ABCC3-associated cisplatin resistance in esophageal cancer cells via the Wnt/β-linked protein signaling pathway." (PMID 37147285, 2023).
malignant peripheral nerve sheath tumor (1 paper, 2022). Malignant peripheral nerve sheath tumor (MPNST) is a rare and often aggressive soft tissue sarcoma occurring in a wide range of anatomical sites. "In particular, ABCB1 and ABCC3 activation and an increase in corresponding protein levels associated with pour prognosis were shown in malignant peripheral nerve sheath tumor (MPNST)." (PMID 35328603, 2022).
oral squamous cell carcinoma (1 paper, 2023). "ABCC3 has been proposed as a potential therapeutic target in cancer, and the RBP1-CKAP4 axis has been found to activate oncogenic autophagy and promote cancer progression in oral squamous cell carcinoma." (PMID 37795080, 2023).
pancreatic adenocarcinoma (1 paper, 2020). "High expression of ABCC3 was correlative with poor prognosis of head and neck squamous carcinoma (HNSC), kidney renal clear cell carcinoma (KIPR), brain lower grade glioma (LGG), pancreatic adenocarcinoma (PAAD) and uveal melanoma(UVM)." (PMID 32161779, 2020).
pancreatic ductal adenocarcinoma (1 paper, 2025). An infiltrating adenocarcinoma that arises from the epithelial cells of the pancreas. "For instance, its overexpression in pancreatic ductal adenocarcinoma (PDAC) cell lines and clinical specimens has identified ABCC3 as a potential therapeutic target in PDAC." (PMID 41304944, 2025).
primary biliary cirrhosis (1 paper, 2023). "Increased expression of Abcc3 and Abcc4 is, thus, in agreement with the observation in earlier studies in primary biliary cirrhosis and acetaminophen-induced liver failure." (PMID 38053838, 2023).
rectal cancer (1 paper, 2025). A primary or metastatic malignant neoplasm that affects the rectum. "However, the association between tumor response and ABCC3 and TYMS gene expression remained significant even after excluding rectal cancer patients who underwent preoperative radiotherapy." (PMID 40357991, 2025). "Specifically, ABCC3 and TYMS expression in rectal cancer were notably different in group 1 (p = 0.045 and p = 0.0056, respectively), whereas lower RFC‐1 expression was observed in both group 1 (p = 0.011) and group 2 (p = 0.0087)." (PMID 40357991, 2025). "Given the potential influence of preoperative radiotherapy on ABCC3 and TYMS expression, the statistical analysis was repeated after excluding rectal cancer patients who received radiotherapy." (PMID 40357991, 2025).
rectal tumors (1 paper, 2025). "ABCC3 expression was significantly lower (p < 0.0001) and TYMS expression significantly higher (p = 0.0006) in rectal tumors subjected to radiotherapy (n = 43) compared to those that were not (n = 36)." (PMID 40357991, 2025).
renal carcinoma (1 paper, 2021). A carcinoma arising from the epithelium of the renal parenchyma or the renal pelvis. "There are eight, five, and eight datasets of ABCC3, ABCF1, and ABCG1 for renal cancer, respectively." (PMID 33825659, 2021).
cancer (84 papers, 1996 to 2025). A tumor composed of atypical neoplastic, often pleomorphic cells that invade other tissues. "ATP-binding cassette subfamily C member 3 (ABCC3), also named multidrug resistance-associated protein 3 (MRP3), is an organic anion transporter and contributes to drug resistance of cancer cells." (PMID 34295296, 2021). "Although the drug transporters ABCG2, ABCB1 and ABCC1 have been majorly implicated in cancer drug resistance, recent studies have associated ABCC3 with multi drug resistance and poor clinical response." (PMID 27171227, 2016). "The ABCC3 gene encodes multidrug resistance-associated protein 3 (MRP3), which is involved in chemotherapy resistance of cancer cells." (PMID 22900095, 2012). "In vitro experiments demonstrated that dimethoxycurcumin significantly reduced cancer cell viability and colony formation, indicating a strong inhibitory effect on ABCC3 function." (PMID 40427480, 2025). "Irradiated GDC0941 and COMP-treated GDC0941 and COMP-treated cells exhibited lower protein expression of ABCC3, a protein involved in treatment resistance in NSCLC and other cancers, and MT-CO1, a mitochondrial protein associated with cancer progression." (PMID 40141111, 2025). "We found that the TSIRS was negatively correlated with cancer stemness (mRNAsi) and positively correlated with the expression of multi-drug resistance associated protein (ABCC2, ABCC3, ABCC6 and ABCC10)." (PMID 36467413, 2022). "In our previous publications, we reported several new molecules potentially involved in the resistance of cancer cells to taxanes, such as ABCC3, CPS1, and TRIP6." (PMID 35008510, 2021). "As one of the ATP-Binding Cassette (ABC) transporters, ABCC3 (also known as MRP3) is commonly overexpressed in many cancer types and mediates tumorigenesis, growth and chemoresistance by interacting with microenvironment cells." (PMID 32725165, 2020). "Since several anti-cancer agents are substrates for ABCC3, screening of other therapeutic agents that can be sensitized by curcumol will be beneficial to establish the new therapeutic strategy." (PMID 33066509, 2020). "ABCC3 knockdown with siRNA significantly lowered cancer cell number and more strikingly, reduced the surrounding fibroblast-like cells." (PMID 31378204, 2019). "Our results show that ABCC3 likely plays a role in tumour-stroma interactions and that ABCC3 inhibition with MCI-715 is a valid strategy for restraining the cancer-favouring role of the tumour microenvironment." (PMID 31378204, 2019). "Similar to ABCB6, ABCC1, and ABCC3 are also capable of effluxing chemotherapeutics of broad function including anti-cancer functions." (PMID 30655622, 2019). "Analysis of established KPC primary cells provided more insight into the importance of ABCC3 in cancer-stroma interactions." (PMID 31378204, 2019). "It has been reported that the expression of ABCC1, ABCC3 or ABCC6 was upregulated in multi-drug resistant cancer." (PMID 29228716, 2017). "The ABCC3 (canalicular multispecific organic anion transporter 2) gene, the 3′ partner in the MED1 (mediator complex subunit 1)-ABCC3 fusion, is known to efflux therapeutic compounds resulting in multidrug resistance in cancer cells." (PMID 28851357, 2017). "Consistent with a reduction in the number of stem-like cancer cells, we observed that knockdown of ABCC3 led to reduced tumor growth compared to control NT cells, which was further reduced on doxorubicin treatment." (PMID 27171227, 2016). "Further, we also investigated the expression of ABCC1 and ABCC3 in various breast cell lines ranging from immortalized to cancer cells." (PMID 27171227, 2016). "To investigate if overexpression of ABCC1 and ABCC3 correlated functionally with drug resistance, we performed doxorubicin retention assays (n = 5) in primary cancer derived cells from the same chemotherapy treated and chemo-naive patient samples." (PMID 27171227, 2016).
cancer (continued). "In addition to ABCB1, increased resistance to DTX is correlated to an upregulated expression of the ABCC3 ATP binding cassette gene, which ultimately diminishes the efficacy of cancer treatment." (PMID 40385549, 2025). "In addition to P-gp and MRP1, other ABC transporters such as MRP6 (ABCC6), MRP2 (ABCC2), MRP7 (ABCC10), and MRP3 (ABCC3) also contribute to the development of drug resistance in various cancers." (PMID 39679367, 2024). "ABCC3 is considered a potential therapeutic target in human cancers and its downregulation here described may explain in part our results." (PMID 38731966, 2024). "Notably, specific mutations were observed in genes involved in lipid localization and transport, including AKR1C1, HDLBP, and ABCC3, suggesting disruptions in lipid metabolism that facilitate the rapid proliferation of cancer cells." (PMID 38010945, 2024). "Also the remaining important genes according to previous studies are cancer-related genes and lead to the development of the tumor and a study of ABCC3 gene whose overexpression indicates poor prognosis in different types of cancer." (PMID 38435719, 2024). "ABCC3/MRP3 plays a crucial role in conferring multidrug resistance to cancer cells." (PMID 35006446, 2021). "ABCC3 has greater expression in many cancers and is also a marker of multidrug resistance." (PMID 34857857, 2021). "Those discoveries revealed the vital role of ABCC3 in cancer development." (PMID 34976054, 2021). "Notably, ABCC3 inhibitors have the potential to not only enhance drug retention but also impede tumor progression by blocking the extrusion of bioactive molecules that contribute to the tumor microenvironment and cancer cell survival." (PMID 40427480, 2025). "ABCC1 and ABCC3 may thus act as prognostic factors in many cancer subsets." (PMID 27171227, 2016). "Regarding the expression of transcripts that are highest in LNCaP-GLI1 cells, ABCC3 is of particularinterest because it encodes a protein that belongs to the ABC (ATP-Binding Cassette)family of transporters that confer drug resistance and that are highly expressed innormal and cancer stem cells." (PMID 21633508, 2011). "Our laboratory has previously demonstrated enrichment of the cancer-type solute carrier organic anion transporter family 1B3 (ct-SLCO1B3) and the ATP Binding Cassette Subfamily Member C (ABCC3) in castration-resistant cell lines (CRPC)." (PMID 38213719, 2024). "It was reported that ABCC3, one of the other prognostic mRNAs estimated by Multi-PEN, has a connection with a poor prognosis and resistance to treatment in cancer." (PMID 36290366, 2022). "Additionally, according to the study, the intracellular concentration and efficacy of drugs are decreased by the exporter that releases the drugs from within the cells; thus, overexpressed ABCC3 creates resistance to multiple drugs for cancers, which may affect the prognosis of LGG." (PMID 36290366, 2022). "Based on our results, we can suggest ABCC3 and CPS1 for further investigations as potential therapeutic targets in human cancers." (PMID 35008510, 2021). "Higher expression of ABCC3 correlated with lymph node involvement, advanced TNM stage, more malignant histological type, multiple-resistance to anti-cancer drugs, and reduced overall survival in NSCLC38,39." (PMID 34857857, 2021). "ABC family members including ABCB1, ABCC1, ABCC2, ABCC3, and ABCG2 were critical for CDDP resistance of cancer cells." (PMID 33754002, 2021). "Expression of the major ABC transporters, including ABCA1, ABCB1, ABCC1, ABCC2, ABCC3 and ABCG2, was assessed in chemoresistant cancer cells transfected with si-ERRγ." (PMID 32206097, 2020). "ATP-binding cassette subfamily C member 3 (ABCC3) is one of the members of ABC transporter subfamily and is able to confer doxorubicin resistance in cancer cells by limiting intracellular concentrations of doxorubicin." (PMID 33066509, 2020).